INS (insulin)
Diseases named in the same sentence as INS in open-access papers (continued):
Sharing a sentence is not in itself a finding about the gene and the disease.
diabetes (continued). "We also demonstrated in the second study that the MFDM powder formula had similar glucose and insulin responses when compared with a commercially available diabetes-specific formula (DSF) in adults at risk for or diagnosed with early diabetes." (PMID 37293492, 2023). "Traditional methods of diabetes treatment have many deficiencies and limitations, such as the inconvenience of repeated insulin injection and side effects of oral chemical drugs." (PMID 37384125, 2023). "To identify the risk of insulin requirement, we selected patients with diabetes who were receiving insulin treatment." (PMID 36831436, 2023). "Patients with insulin-treated diabetes were at significantly higher risk for returning to the operating room (p < 0.0001)." (PMID 36835979, 2023). "Diabetes mellitus (DM) is a metabolic disease related to chronic hyperglycemia caused by impaired insulin secretion and/or action." (PMID 37509724, 2023). "Two of these sites (F48, F49) are known to have variants associated with pathogenic monogenic diabetes, with F48C being one of the three most common insulin variants in neonatal diabetes." (PMID 36830626, 2023). "Diabetes mellitus (DM), a chronic endocrine disorder, caused by insufficient production or abnormal secretion of insulin from the pancreas." (PMID 37631233, 2023). "The third state includes factors associated with the chronic management of diabetes, such as recurrent hypoglycemic episodes, strict insulin treatment, and carbohydrate counting." (PMID 36837546, 2023). "Diabetes mellitus (DM) is a chronic disorder affecting carbohydrate metabolism and involving hyperglycemia, as a result of deficiencies in insulin release, action, or even both." (PMID 36973339, 2023). "Studies have shown that melatonin inhibited the secretion of insulin from pancreatic β-cells through the melatonin receptor 1b gene, thereby increasing blood sugar levels and increasing the risk of diabetes." (PMID 37310940, 2023). "These enzymes can also reduce the damage caused by diseases such as diabetes, insulin cell damage, and atherosclerosis due to oxidative stress, and slow down the aging of the body." (PMID 37346299, 2023). "Diabetes is a chronic, common, and multifactorial disease defined by hyperglycemia caused by reduced insulin production or insulin resistance, leaving the body unable to completely respond to insulin." (PMID 37324874, 2023). "These hormones work against insulin, causing the body to produce more glucose, which can result in diabetes." (PMID 37388615, 2023). "The overexpression of miR-143 targets an oxysterol-binding protein-related protein (ORP8), leading to its downregulation and impairing insulin-induced AKT activation in obesity-associated diabetes." (PMID 37371692, 2023). "Our research shows that both diabetes and hyperglycemia are risk factors for aortic remodeling, whereas insulin resistance affects the left ventricle." (PMID 38066511, 2023). "Being on insulin alone and a duration of diabetes treatment equal or more than 7 years predisposed to poor glycaemic control." (PMID 38076524, 2023). "For diabetes’ risk markers (fasting blood glucose, fasting insulin, HbA1c), significant changes only were observed within groups." (PMID 37892536, 2023). "Dysfunction of the endoplasmic reticulum (ER) in insulin‐producing beta cells results in cell loss and diabetes mellitus." (PMID 36704923, 2023). "As a result, they identified the two phagotopes (phage that carry peptides that mimic epitopes), designated IAS-9 and IDD-10, which were able to discriminate between diabetes-associated and non-diabetes associated insulin antibodies." (PMID 37373160, 2023). "In particular, biological sex plays a significant role in the development of metabolic diseases associated with insulin dysfunction, such as diabetes, cardiovascular diseases, and NAFLD." (PMID 36942499, 2023).
diabetes (continued). "Before taking insulin treatment into practice, bacterial infection was recognized as one of the most serious complications of diabetes mellitus, and it has been considered a critical cause of morbidity and mortality among diabetic patients." (PMID 38003764, 2023). "Type 2 diabetes mellitus (T2DM) is a chronic endocrine metabolic disease caused by insulin dysregulation." (PMID 37293508, 2023). "Mechanisms for the association between insulin-requiring diabetes and a higher bleeding risk are unclear, with a possible role of micro-angiopathy in patients suffering from long-lasting disease and a hyperglycemia-related vascular leakage being here invoked." (PMID 35976428, 2023). "A recent study in adults identified five unique diabetes subgroups qualitatively grouped by presence of autoimmune antibodies, insulin deficient, insulin resistant, obesity related, and age-related diabetes." (PMID 38694145, 2023). "This puts pressure on the pancreas to produce more insulin, which causes a gradual destruction of beta cells, and leads to pre-diabetes and T2D." (PMID 37316893, 2023). "Diabetes mellitus (DM) is a chronic metabolic disease characterized by hyperglycemia that results from deficiencies in insulin secretion and/or action." (PMID 36800369, 2023). "For example, gut microbiota signatures can be used to identify individuals at higher risk for diabetes and act as a target for microbial alterations to improve insulin sensitivity." (PMID 37189387, 2023). "In the case of deficient insulin production, the association with type 1 diabetes mellitus is known, where the destruction of pancreatic beta cells seems to be important above all by means of immune-mediated mechanisms." (PMID 37371857, 2023). "The association remained stable after further adjustment for diabetes duration, antidiabetic medicine, and insulin use." (PMID 37161588, 2023). "Adequate sleep, on the other hand, can improve insulin sensitivity, reduce appetite, and promote weight loss, reducing the risk of diabetes and obesity." (PMID 37600709, 2023). "Hyperglycemia seen in diabetics stems from either the inability to produce insulin through beta cell loss (Type 1 Diabetes, T1D) or through an accumulated resistance to insulin (Type 2 Diabetes, T2D)." (PMID 37483613, 2023). "The risk of hypoglycemia is a major concern for people with insulin-treated diabetes and their relatives." (PMID 38089060, 2023). "Diabetes is a chronic disease generally caused by a dysfunctional pancreas that does not produce enough insulin or by the body’s ineffective use of the insulin produced." (PMID 38003764, 2023). "Inadequate insulin causes the metabolic syndrome known as diabetes mellitus, which leads to hyperglycemia and insufficient cell glucose uptake." (PMID 37687218, 2023). "Between 5% and 10% of all diabetics have type 1 diabetes, often known as “juvenile” diabetes, which is caused by the pancreas’ failure to release insulin as a result of certain genetic and environmental variables." (PMID 37240812, 2023). "Defective O-GlcNAcylation of proteins involved in insulin signaling has been associated with hyperglycemia, insulin resistance, and diabetes." (PMID 37107691, 2023). "The strongest risk factors for UTI are previous UTI and insulin-treated diabetes while female sex, obesity, and genetic susceptibility have shown to be minor risk factors." (PMID 37760688, 2023). "Insulin therapy serves the purpose of regulating blood glucose levels and preventing complications associated with diabetes." (PMID 37915365, 2023). "The detection of circRNA in the blood stream has been associated with the control of insulin production as well as the development of diabetes." (PMID 36890575, 2023). "Kamoda and coworkers described the case of an infant with SDS with slowly deteriorating glucose homeostasis from 3 weeks of age until the diagnostic criteria for overt diabetes mellitus were met at 15 months, requiring insulin therapy." (PMID 37580732, 2023).
diabetes (continued). "This realization can bring about a heightened awareness of the seriousness of the disease, leading to concerns about potential diabetes-related complications and the side effects associated with insulin use." (PMID 37893847, 2023). "A higher prevalence of hypertension, diabetes mellitus, diabetes as the cause of dialysis, multivessel disease, insulin therapy, and beta-blocker therapy was observed among patients in the third TyG index tertile compared to those in the first tertile." (PMID 37848993, 2023). "In a study on STZ‐induced diabetic mouse models, lycopene downregulated diabetes‐associated pancreatic injuries, reduced glucose levels in urine and blood, and upregulated serum insulin levels." (PMID 37823149, 2023). "We ascertained that the diabetes severity score, which included measures of the use of insulin and multiple OHAs, duration of diabetes, and the presence of CKD or CVD, was associated with TB risk in a dose-dependent manner." (PMID 37041513, 2023). "Type I diabetes mellitus is an insulin-dependent diabetes mellitus that is caused by a deficiency in the secretion of insulin in the pancreas due to the destruction of pancreatic β cells." (PMID 37111730, 2023). "Impaired insulin signaling, including mutations in the insulin receptor tyrosine kinase (5hhw), is present in most diabetes mellitus patients." (PMID 38601799, 2023). "Diabetes mellitus is a global epidemic afflicting >500M adults world-wide and is associated with dysfunction or death of insulin-producing β-cells within pancreatic islets." (PMID 38018905, 2023). "In conclusion, our findings suggest a sleeping-brain—glycemic-body framework of insulin-associated glucose homeostasis in humans, and further re-emphasize the importance of sleep in the clinical management of hyperglycemia and diabetes." (PMID 37421946, 2023). "The strong relationship between diabetes and HF results from the deleterious influence of key pathogenic variables, including chronic glucotoxicity, lipotoxicity, and altered insulin signalling." (PMID 37109700, 2023). "Hyperglycemia, a reduction in insulin, and the loss of the beta cells’ microscopic structure in the pancreatic islets of Langerhans make up the global problem of diabetes mellitus." (PMID 36932309, 2023). "A gradual decline in the BMI is also a hallmark of diabetes, but early screening and insulin therapy appear to ameliorate the clinical course." (PMID 38136081, 2023). "In patients with diabetes, weight loss is a marker of disease severity and loss of physical reserve and insufficient insulin secretion." (PMID 38017465, 2023). "Diabetes mellitus is a metabolic disorder characterized by high blood sugar levels or hyperglycemia that is caused by problems with insulin secretion, insulin action, or both and it is related to carbohydrate, lipid, and protein metabolism derangements." (PMID 37755075, 2023). "In fact, in a large cohort study, younger age at onset of diabetes increased the risk of subsequent dementia where AD has been called “type 3 diabetes” due to insulin resistance where mitochondrial dysfunction and reduced ATP supply has been implicated." (PMID 37509027, 2023). "Diabetes mellitus (DM) is a chronic metabolic disorder characterised by hyperglycaemia caused by complete or partial insufficiency of insulin secretion and insulin action." (PMID 37239204, 2023). "Diabetes mellitus is a metabolic disease caused by impaired production of insulin or resistance to it and is characterized by the abnormal metabolism of glucose, proteins and lipids." (PMID 37775939, 2023). "Gla-300 has shown improved glycemic control with stable insulin action and low risk of hypoglycemia in diverse groups with diabetes." (PMID 36624651, 2023). "Increased duration of diabetes is associated with reduced ß cell mass, which leads to insulin deficiency and the need for insulin therapy to achieve glycemic control in many older adults with long-standing T2DM." (PMID 37993898, 2023).
diabetes (continued). "Diabetes is a chronic disease caused by insufficient insulin secretion or reduced insulin sensitivity." (PMID 38028597, 2023). "Exenatide and liraglutide were shown to prevent and reverse diabetes, enhance insulin secretion, and reduce neuroinflammation and vision loss in rodent models of Wolfram syndrome." (PMID 36995380, 2023). "Among these beneficial bacteria, Bifidobacterium and Lactobacillus can improve blood glucose abnormalities and insulin sensitivity and can potentially reduce the risk of diabetes development." (PMID 37893758, 2023). "The long-term exposure of body tissues to high circulating insulin levels induced certain metabolic modifications in adipose tissue, causing various health problems, including risks of metabolic syndrome and diabetes." (PMID 37512149, 2023). "The pathogenesis of diabetes-associated cognitive decline is related to several factors, such as brain insulin resistance, mitochondrial damage, oxidative stress, calcium homeostasis imbalance, and inflammatory response." (PMID 37759725, 2023). "The key pathogenic mechanism for diabetes in HH is insulin deficiency, and a causal role for iron has been demonstrated by improvements in insulin secretion after iron reduction by phlebotomy." (PMID 36137277, 2023). "The improved safety of insulin treatment in this high-risk group of patients is in line with a previous publication showing the use of flash CGM is associated with reduced diabetes events and hospitalizations in insulin treated T2DM." (PMID 37993898, 2023). "Insulin resistance (IR), a state of peripheral tissue insensitivity to insulin, is known to be a key pathogenic characteristic of type 2 diabetes mellitus (DM)." (PMID 37202751, 2023). "The risk of diabetes-related hospitalization increased with age, female gender, insulin use, chronic renal insufficiency, and hypoglycemia." (PMID 37149604, 2023). "Contrary to T1D, Type 2 diabetes (T2D) is associated with a developed resistance to insulin, accounting for ~90% of individuals with diabetes." (PMID 36830626, 2023). "A positive association of branch-chain amino acids in diabetes had been concluded by modulating insulin secretion and leading to the pancreaticb-cell exhaustion." (PMID 36984900, 2023). "This disease is most often found in patients with diabetes, usually treated with insulin, but it has also been described as associated with monoclonal gammopathy." (PMID 36768300, 2023). "Diabetes mellitus is a group of metabolic diseases characterized by permanent hyperglycemia, resulting from absolute or relative insulin deficiency, insulin action or both." (PMID 38019818, 2023). "Calpain10 (CAPN10) gene was the first identified susceptibility gene for type 2 diabetes mellitus and closely related to insulin sensitivity." (PMID 37727373, 2023). "After adjusting for age, sex, BMI, smoking, drinking, insulin treatment, higher number (≥ 3) of antidiabetic medications used, and duration of diabetes (≥ 5 years), higher SBP showed a trend of increased AF risk without statistical significance." (PMID 37014888, 2023). "There are rarer forms of diabetes, including monogenic diabetes, which results from specific gene mutations affecting insulin production or function." (PMID 38022307, 2023). "The adjusted HR for insulin requirement among patients with diabetes associated with cancer development was 1.43 (95% CI, 1.14–1.78)." (PMID 36831436, 2023). "Regular exercise can improve insulin sensitivity, glucose uptake, and body weight, reducing the risk of diabetes and obesity." (PMID 37600709, 2023). "Type 2 diabetes mellitus (TII DM) is caused by a gradual loss of βeta-cell’s ability for insulin secretion sufficiently, almost in the presence of insulin resistance." (PMID 37964303, 2023). "In analogy to what was observed for renin, recessive INS mutations leading to early-onset diabetes are loss-of-function mutations." (PMID 37283036, 2023).
diabetes (continued). "Some circRNAs have been linked to the progression of diabetes, including reducing β-cell proliferation, decreasing survival, and impacting insulin secretion." (PMID 36818396, 2023). "Diabetes comprises a collection of metabolic conditions characterized and identified by hyperglycemia due to the deficiency of insulin secretion, impaired insulin action, or both." (PMID 37174622, 2023). "On the other hand, metabolic diseases, such as diabetes, are characterized by glucose and insulin dysfunctions, and have been documented to be associated with an increased risk of developing AD." (PMID 38283741, 2023). "The objective of this research was to investigate the risk of type 2 diabetes development, insulin requirements, and diabetes-related complications in patients with cancer." (PMID 36831436, 2023). "Type 1 diabetes mellitus can be caused by insulin production deficiency, while Type 2 diabetes mellitus results from the insufficiency or inefficacy of insulin produced." (PMID 37375357, 2023). "The highest prevalence of T1DM was observed in ages between 75 and 79 years due to improved diabetes care, availability of insulin, and increased survival of T1DM patients, that cause most patients to reach older ages." (PMID 36918650, 2023). "In model 2, which was adjusted for model 1 + diabetes duration, cardiovascular diseases history, and drug usage (ARBs, ACEIs, beta-blockers, metformin, sulphonyl urea, and insulin), the inverse association remained (OR: 0.16; 95% CI 0.07–0.34; P < 0.001)." (PMID 36782160, 2023). "Their concentrations were found to be markedly elevated in insulin-deficient diabetes, particularly in the extreme condition of ketoacidosis." (PMID 38201949, 2023). "Dysregulation of insulin and estrogen signaling causes metabolic diseases, such as obesity, diabetes, cardiovascular diseases, muscle diseases, liver diseases, and neurodegenerative diseases." (PMID 36942499, 2023). "Bizarrely, TLR9 deficiency was found to boost glucose tolerance and insulin sensitivity in individuals with diabetes." (PMID 37998038, 2023). "Compared with T2DM, post-pancreatitis diabetes is associated with poor glycemic control, a much higher insulin requirement, a higher risk of developing cancer, death at an earlier age, and a significantly higher risk of death." (PMID 36979645, 2023). "On the other hand, the negatively associated genes were involved in insulin and pancreatic secretions that can hamper the normal physiology of pancreas leading to several chronic diseases like pancreatitis, diabetes, and pancreatic cancer." (PMID 38074464, 2023). "The interplay of traditional risk factors such as obesity, energy-dense diets, and physical inactivity is implicated in reduced insulin secretion, increased insulin resistance, and the development of diabetes mellitus." (PMID 37266136, 2023). "Secretory granules indirectly affect blood glucose levels by regulating insulin secretion, and diabetes is a clinical risk factor for OP." (PMID 38260098, 2023). "Studies have also linked high ghrelin concentration with increased insulin secretion and development of obesity in diabetes which was also shown in untreated HFHC prediabetic rats in this study." (PMID 38096150, 2023). "Taking into account the disproportional growth, final body weight, glucose, and insulin concentration, the risk of diabetes mellitus and obesity should be considered." (PMID 37174575, 2023). "Diabetes mellitus is a long-term metabolic problem that causes high blood glucose levels because the body cannot make or use insulin properly." (PMID 37746454, 2023). "Diabetes is recognized for its impact on glucose and insulin metabolism, and it is commonly linked to the presence of chronic inflammation." (PMID 38098008, 2023). "Insufficient insulin frequently caused fast, considerable weight loss in diabetes mellitus patients." (PMID 36973339, 2023).